CD14 (CD14 molecule)
Diseases named in the same sentence as CD14 in open-access papers (continued):
Sharing a sentence is not in itself a finding about the gene and the disease.
tumor (continued). "In order to mimic the crosstalk of immune cells and tumor cells in the in vitro 3D model, we co-cultured three-day-old tumor spheroids with CD14+ immune cells." (PMID 33808732, 2021). "CD14+ tumor-infiltrating cells expressed higher levels of PD-L1 and CD209 than circulating T cells, while a higher percentage of tumor-associated CD3+ T cells expressed PD-1." (PMID 34945784, 2021). "In order to assess the effects of spheroid- and explant-conditioned Mφs on T cell activity, tumour-conditioned or control Mφs were loaded with viral peptides (VP) and co-cultured with CD14− PBMCs for 6 days." (PMID 33804204, 2021). "Treatment with CDA was associated with the reduction in expression of HCL tumour markers (CD20, CD11c) and increased expression of myeloid markers (CD14, CD68, CD66b, ARG1)." (PMID 34561502, 2021). "The results showed that the proportion of CD45+CD14+CD163+ mono-macrophage subset infiltrated by tumor tissue was significantly higher than that in paracarcinoma tissues." (PMID 34803459, 2021). "Oestrogen deprivation of MCF-7 cells increased migration of total PBMCs and, specifically, CD4+ T cells towards tumour cells and slightly reduced CD11c+ and CD14+ cells." (PMID 34602068, 2021). "SHH MB subgroup has increased expression of inflammation-related genes (CD14, PTX3, CD4, CD163, CSF1R, and TGFB2) and significantly higher infiltration of tumour-associated fibroblasts than Grp3 MB and Grp4 MB." (PMID 34195095, 2021). "The PDOTSs showed a smaller myeloid cell population, including monocyte lineage CD14+ cells, than the tumor tissues due to the death of myeloid cells in the PDOTSs." (PMID 34240815, 2021). "Although, the recent identification of CD14 as a marker of to distinguish G-MDSCs from neutrophils in tumor-bearing mice is a promising step toward overcoming this obstacle." (PMID 34944914, 2021). "Further compartmentalization of the tumor compartment into PT Tumor (CD14 p = 0.001; CD68 p < 0.001; CD163 p < 0.001) and IT Tumor (CD14 p < 0.001; CD68 p < 0.001; CD163 p < 0.001) showed similar results." (PMID 34194435, 2021). "CD14+ PBMCs incubated with fibroblast-containing spheroids appeared more M2-like than those incubated with homotypic tumour spheroids." (PMID 33804204, 2021). "Under these conditions, treatment with H22-dPBD effectively eradicated both blood monocytes and tumor-infiltrating CD14+ cells, some of which expressed CD163, a representative TAM marker." (PMID 33692791, 2021). "When CD14+, CD68+ and CD163+ myeloid densities in the intratumoral tumor (IT Tumor) increased, the risk of death was found to decrease slightly but in a statistically significant manner." (PMID 34194435, 2021). "Tumor-associated fibroblasts (TAFs) mediated monocytes’ migration into tumor sites by secreting CXCL12 and induced their transformation into CD14+HLA-DR-/low MDSCs by IL-6 mediated STAT3 activation." (PMID 34680276, 2021). "The level of CD14 expression in CRC increased with tumor budding and was the highest for the Bd3 score (p = 0.0324)." (PMID 33625532, 2021). "The majority of the granulocytes were CD15+CD16+CD14±, corresponding with granulocyte-MDSCs (G-MDSC) or antigen-presenting tumour associated neutrophils, marked by their HLA-DR expression (metacluster 4), although we also observed the co-expression of PD-L1." (PMID 33917832, 2021). "As a key component of the Toll-like receptor (TLR) signaling pathway, CD14 can promote tumor occurrence and development by regulating the activation of different signaling pathways in tumor cells or tumor infiltrating immune cells." (PMID 34195091, 2021). "In this system, PDOs preserved fibroblast stroma that progressively decreased with the passages and contained CD3+ T cells in proximity to tumor epithelium, CD14+, CD68+ NK, and B cells." (PMID 34074330, 2021).
tumor (continued). "Although CD206+ macrophages accounted for the majority of CD14+CD11b+ cells isolated from the tumor, very few were observed in peripheral blood monocytes (PBMs), indicating that CD206+ hTAMs accumulated in the CRC tumor microenvironment." (PMID 34667145, 2021). "While typical macrophage markers such as CD68, FCGR3A, MARCO, and CD14 were highly expressed in TAMs as well as non-tumor macrophage samples, the expression of canonical M1, M2, and TAM markers was more diverse." (PMID 33918618, 2021). "In contrast, CD8+ cell, pDC, total monocyte, CD14+ monocyte and CD 16+ monocyte proportions in tumor tissue were significantly higher in the tumor size > 4 cm group than in the tumor size ≤4 cm group." (PMID 32131750, 2020). "Of note, we observed that CD14+ DCs, isolated from OSCs, were already less stimulatory than cDC2s, but the presence of the tumour further decreased their ability to stimulate T-cell proliferation and activation." (PMID 32488012, 2020). "(D) Relative mRNA expression levels of Cd14, Bcl3, Osmr and Nfkbia between the sorted Neu tumor sub-populations." (PMID 32840210, 2020). "The levels of CD8+ cells, pDCs, total monocytes, CD14+ monocytes and CD 16+ monocytes were significantly higher in the tumor size > 4 cm group than in the tumor size ≤4 cm group (p < 0.05)." (PMID 32131750, 2020). "Several groups have delivered viruses using autologous cells, including mesenchymal stem cells (MSCs), CD14+-derived monocytes and irradiated tumor cells, interleukin-2 (IL-2)-expanded T cells." (PMID 33473255, 2020). "Specifically, the mice were injected with HepG2 cells and then with CD14+ cells from the same patients at early tumor stages (at the time of initial treatment) or at advanced tumor stages." (PMID 32824016, 2020). "We can also detect the presence of CD14+ cells in a sub-population of Neu tumor cells by immuno-histochemistry, validating the scRNA-seq observations." (PMID 32840210, 2020). "By understanding the respective tumor hierarchies, we were able to identify CD14 as a TPC marker in the Neu tumor." (PMID 32840210, 2020). "The authors found out that this treatment reduced tumor infiltrating CD14+ monocytes and CD19+ B cells while increasing tumor infiltrating CD56+ natural killer cells." (PMID 33114769, 2020). "Specifically, the tumor tissue expressed higher levels of cd14 and cd68 indicative of a greater presence of monocytes and macrophages in the tumor tissue compared with NAT." (PMID 32737216, 2020). "Within the OMC, we observe the tumour-driven conversion of cDC2s into CD14+ DCs, characterized by an immunosuppressive phenotype." (PMID 32488012, 2020). "Classical IMOs (CCR2HighLy6C+ in mice; CCR2High CD14+CD16- in humans) promote tumor metastasis upon their recruitment to tumor sites." (PMID 33203789, 2020). "Ex vivo tumour-infiltrating CD14+ DCs are characterized by the expression of the T-cell inhibitory molecule PD-L1." (PMID 32488012, 2020). "i.e. HLA-DR−/lowCD14+ M-MDSCs and HLA-DR+CD14+ MO/MA among mononuclear cells (MCs) isolated from the three TMEs including blood, ascites and tumour tissue." (PMID 32487171, 2020). "THP1-Blue/ THP1-Blue-CD14 cells are myelomonocytic tumor cells, while PBMC originate from healthy donors comprising various frequencies of lymphocytes including T cells and monocytes, but also B cells, NK cells, and dendritic cells." (PMID 32098277, 2020). "To functionally characterize tumour-induced CD14+ DCs, we next performed qRT-PCR on cDC2s and CD14+ DCs FAC-sorted 18 h post-injection." (PMID 32488012, 2020). "The MDSC populations were marked as eMDSC (Lineage–CD11b+CD33+), amounting at 0.06%, and as PMN-MDSC (CD45+CD15+CD14–CD11b+), amounting at 0.11% of the total tumor cell suspension in GCT." (PMID 32814714, 2020).
tumor (continued). "Studies of the same tumor specimens revealed that the majority (∼80%) of tumor-associated DCs (TADCs), defined as CD45+CD11c+HLA-DR+ cells, expressed CD14, which indicates their monocytic origin and likely inclusion among the CD14+ cells associated with Tregs." (PMID 32973804, 2020). "Although the percentage of CD45+ immune cells varied noticeably in individual tumours, CD14+ monocyte cells were the most dominant population within all tumours, representing over 90% of the CD45-positive immune infiltrate in samples tested." (PMID 32070062, 2020). "Total monocyte and CD14+ monocyte frequencies were significantly decreased in the tumor tissue compared to the peripheral blood (p < 0.05)." (PMID 32131750, 2020). "On the basis of their immunosuppressive activity, CD14+HLA-DRlow monocytes are often referred to as M(o)-MDSCs, analogous to T-cell suppressive mouse monocytes isolated from the spleen of tumor-bearing mice." (PMID 33042791, 2020). "Our study found that the levels of total monocytes and CD14+ monocytes were significantly decreased in tumor tissue compared to the peripheral blood, while the level of CD16+ monocyte was significantly elevated." (PMID 32131750, 2020). "CD14+ cells were also isolated from five naïve advanced-stage HCC patients before treatment as well as after treatment-induced tumor regression." (PMID 32824016, 2020). "Multiplex immunofluorescence staining was performed to quantify CD163, HLA-DRA and CD14 expression in the tumour area annotated by AMACR staining." (PMID 32908142, 2020). "(A) t-SNE plots showing the expression levels of Cd14, Bcl3, Osmr and Nfkbia in the Neu tumor sub-clusters." (PMID 32840210, 2020). "Monocytic myeloid-derived suppressor cells (M-MDSCs) characterized with the phenotype of CD14+HLA-DRlow/- have attracted a lot of attention in the field of human tumor immunology." (PMID 33415170, 2020). "Tumor-associated macrophages are often identified by the immunophenotype CD68+ CD14+ and the number of macrophages correlates with tumor growth and prognosis." (PMID 31491903, 2019). "Similar to the findings in COPD, tumor infiltrating CD14+ cells in patients with early lung cancer express a mixture of FcγRs (CD64, CD32), cytokine receptors (CD115) and scavenger receptors (CD163, CD206)." (PMID 31543877, 2019). "The CD14+ myeloid population (putative M-MDSCs) was also increased in tumor-bearing dogs (0.20% [0.06, 0.57]) when compared to healthy control dogs (0.14% [0.05, 0.24]; p = 0.018) but not those with inflammatory disease (0.28% [0.12, 0.64]; p = 0.72)." (PMID 30837603, 2019). "Previous studies have shown that Mo/MΦs commonly lose CD14 expression particularly when present in tumor tissue and other markers are utilized to define these subsets of Mo/MΦs6,26,27." (PMID 31611550, 2019). "These images have been analyzed in full analogy to the tumor subsections, obtaining counts and densities for CD14- and CD163-positive macrophages, to be investigated for possible correlations with the documented clinical outcome." (PMID 31303867, 2019). "DCs can be generated ex vivo from CD14+ monocytes, loaded with different LAAs or tumor antigens, and they can be re-administrated to the patient as vaccine." (PMID 31533251, 2019). "We then explored the effect of CCR2 blockade on Mφs polarization by separating CD14+ cells from the tumor mass and using quantitative RT-PCR to detect expression of Mφs polarization-associated genes." (PMID 31611552, 2019). "We reported that tumor-derived exosomes were efficiently internalized by CD14+ monocytes and were able to modulate their production of inflammatory proteins." (PMID 31186484, 2019). "D) The percentage of CD68+ CD14+ cells is increased following tumour polarisation, compared to the mean of unpolarised cells (RED)." (PMID 31462392, 2019).
tumor (continued). "Within mouse cell populations (HLA−), there was a significantly higher population of CD14+ cells, indicating mouse-derived immune cell invasion into the tumor, as would be expected after consecutive passaging in mice." (PMID 30845999, 2019). "To address this, we first established a protocol for the reproducible isolation of CD14+ cells from venous blood and tumor tissue." (PMID 31155685, 2019). "Supposedly, CD14+CD16−HLA-DRhi monocyte promotes the infiltration of T cell from peripheral blood into tumor bed which results in enhanced T cell-mediated tumor killing activity." (PMID 30139382, 2018). "We assessed the integration and localization of monocytes within the spheroids by adding purified blood CD14+ cells to the mixture of tumor cells and dermal fibroblasts at equal density of 104 cells per drop." (PMID 30400822, 2018). "The expression of molecules expressed by immune cells such as CD14 will be dependent on the overall presence of these cells in the tumour microenvironment." (PMID 30413173, 2018). "Intense membranous CD14 staining was predominately found on tumor-infiltrating leukocytes, and rarely on cancer cells." (PMID 29777108, 2018). "PD-L1 was upregulated both on target tumor cells and on CD14+ monocytes embedded in the 3D device collagen gel after 48 hr of culture with pro-inflammatory cytokines and even more strikingly after the addition of antigen-specific T cells." (PMID 30217730, 2018). "As expected, CD14+ cells in tumour tissue exhibited an M2-like alternative phenotype, as shown by their higher expression of CD64 and CD163 with respect to peritumours." (PMID 30285662, 2018). "CD14+HLA-DR+ macrophages constituted 4.7% of all tumor-infiltrating leukocytes whereas the three DC populations together represented 2.1% of all leukocytes in tumor." (PMID 30774636, 2018). "The percentage of CD14+HLA-DR+ macrophages was lower in tumor (for adenocarcinoma and all NSCLC patients) compared to distal lung." (PMID 30774636, 2018). "These scavenger cells that contain tumor material in their cytoplasm (“stomach contents”) can be identified in whole blood samples by the fact that they bear the surface markers CD14 and CD16." (PMID 28425973, 2017). "Analysis of the cellular infiltrate in spleens from tumor-bearing animals in comparison to control mice allowed for definition of subset of monocytes (CD3-CD19-CD11b+CD14+), increased in 4T1.2 tumor-bearing animals as compared to 67NR." (PMID 28744322, 2017). "For example, CCL2 and IL-6 were found to contribute to the survival of CD11b+ myeloid monocytes recruited to the tumor microenvironment and skew the phenotype toward tumor-promoting CD14+/CD206+ M2-type macrophages." (PMID 28948005, 2017). "There was higher levels of CD14-positive cells detected in metastatic tumours compared to the indolent tumours." (PMID 28382931, 2017). "We observed in our 3D co-culture model that tumor/fibroblast spheroids induced an M2 polarization of co-cultured monocytes with a CD14+ CD163+ HLA-DRlow CD86low ARG-1+ phenotype which resembles the phenotype of TAMs in PDAC." (PMID 28750018, 2017). "We observed a significant increase in the frequency of CD3-CD19-CD11b+CD14+monocytes in 67NR and 4T1.2 tumor-bearing mice." (PMID 28744322, 2017). "Both CD14+ MDSCs and tumor infiltrated macrophage differentiate from CD14+ myelomonocytic cells, with similar function in tumor environment." (PMID 28533507, 2017). "The presence of tumor markers in blood cells that bear the surface markers CD14 and CD16 was first discovered by the presence of PSA in these cells." (PMID 28425973, 2017). "Surprisingly, HLA-DRlo cells represented a minority (∼15%) of the CD14+ monocyte population within the tumour specimen itself, with the majority of monocyte lineage cells displaying surface markers consistent with traditional monocytes (CD14+CD33+HLA-DRhi)." (PMID 28146145, 2017).
tumor (continued). "The down-regulated genes included the following: 1) immune system activators such as CD14 and CD1d; 2) hematopoietic tumor suppressor IRF822; and 3) ZFP36L1, a promotor of monocyte/macrophage differentiation that represses CDK623." (PMID 27686215, 2016). "It was observed that the effect on blocking the decrease of CD14 and CD1a appearance was restricted to microvesicles-free supernatant, thus eliminating the role of these tumor microvesicles at least on the CD14 and CD1a modulation." (PMID 27088097, 2016). "They found that the level of CD14+HLA-DRlo/neg monocytes in the peripheral blood of these patients correlated with the intensity of CD14 staining in tumours and adversely affected survival." (PMID 27355390, 2016). "Our results demonstrated that the level of TREM-1 on CD45+CD14+ monocyte/macrophage from tumor tissue displays a significantly lower than that from corresponding distal nontumor lung tissues." (PMID 27244892, 2016). "One report shows that the treatment of CCL2 with peroxynitrite resulted in an impaired capacity to attract antigen-specific CD8+ T cells into the tumor tissue in mice, whereas CD14+ monocyte chemotaxis remained unaltered." (PMID 27566567, 2016). "In this study, we detected a significantly higher frequency of circulating and tumor infiltrating CD14+CD169+CD163+ and CD14+CD163+CD206+ M2-like macrophages in CRC patients." (PMID 26509874, 2015). "LPS-activated CD14+ CD11c+ human phagocytes expressed significantly higher levels of the inflammatory macrophage/DC marker CD80 in tumor spheroids, which again further increased upon addition of IFN-γ." (PMID 25871398, 2015). "As expected, expression of HLA-DR and CD86, which are well known as markers of M1 macrophages, were up-regulated on CD14+ monocytes within PBMC co-cultured with tumor cells in the presence of cetuximab (p = 0.004)." (PMID 26579227, 2015). "The percentages of CD14+CD169+ macrophages in TIMs were significantly higher than that in LPMCs of non-tumor patients (25.36% vs. 1.83%, P<0.0001)." (PMID 26509874, 2015). "Dissociated tumor tissue cell suspensions were subjected to flow cytometry and forward/side scatter, CD14, and CD56 staining was used to distinguish the cancer cell, monocyte, and lymphocyte populations." (PMID 25655677, 2015). "CD14+ naïve monocytes from the co-cultures of tumor cells, cetuximab and HNSCC patient PBMC or purified monocytes were skewed to an M1-like phenotype, with increased expression of HLA-DR, CD86 and production of IL-12 p70." (PMID 26579227, 2015). "CD3 cell surface marker was used for lymphocyte identification in addition to CD14 identification in tumor tissues." (PMID 26286851, 2015). "Similar changes of surface markers on CD14+ monocytes were also observed in the co-cultures of tumor cells and purified monocytes with cetuximab in the absence of NK cells, indicating M1/M2 skewing of naïve monocytes altered by cetuximab is NK-independent." (PMID 26579227, 2015). "CD14+ monocytes showed significantly decreased CD16 surface expression when cultured with cetuximab-coated tumor cells (p = 0.004), concomitant with upregulation of M1 and down-regulation of M2 markers." (PMID 26579227, 2015). "CX3CL1-driven chemotaxis and adhesion are mediated by CX3CR1 that is expressed on different cell types such as NK cells, CD14+ monocytes, cytotoxic effector T cells, B cells, neurons, microglia, smooth muscle cells, and tumor cells." (PMID 24799766, 2014). "The abnormal accumulation of CD14+HLA-DR− cells reportedly contributes to tumor immune evasion and correlates with cancer prognosis." (PMID 25238263, 2014). "The CD14+HLA-DR- subset of MDSCs was reported to contribute to tumor progression and treatment resistance in non-small lung cancer and head and neck SCC." (PMID 25238263, 2014). "According to our previous study, tumor cells are relatively sensitive to lapatinib as compared to normal counterparts like human CD14+ monocytes or mouse bone-marrow cells." (PMID 24947784, 2014).